KRT19 (keratin 19)
Diseases named in the same sentence as KRT19 in open-access papers (continued):
Sharing a sentence is not in itself a finding about the gene and the disease.
breast carcinoma (continued). "As KRT19 expressed in various cancer types, we checked the expression level of KRT19 in five paired breast cancer tissue and adjacent normal breast tissues using reverse transcriptase-polymerase chain reaction (RT-PCR) analysis." (PMID 29747452, 2018). "Our previous study reported that the expression of KRT19 was upregulated in various breast cancer cell lines (i.e., MDA-MB231, MCF7) and was downregulated in highly aggressive cancer stem-like cells." (PMID 29747452, 2018). "The third ranked gene KRT19 has been widely reported to contribute to breast cancer tumorigenesis by its involvement in the organization of myofibers." (PMID 29534550, 2018). "To explore the function of KRT19 on cell migration in breast cancer, we first performed a wound healing cell migration analysis." (PMID 29747452, 2018). "KRT19 was also found to be a regulator of p38-MAPK/XBP-1 signaling cascade-mediated endoplasmic reticulum stress in breast cancer." (PMID 29747452, 2018). "KRT19 is the smallest and atypical in its class of keratins and is altered in cancers including pancreatic, hepatocellular and breast cancer." (PMID 28344825, 2017). "We defined CTC_EP based on expression of KRT19, an epithelial marker, commonly utilized for CTCs detection with established prognostic value in breast cancer." (PMID 26896000, 2016). "In this study, we present an automated processing procedure with two variant methods developed in Fiji for quantifying the IHC marker cytokeratin-19 (CK19) in breast cancer tissues using DIs of TMA cylinders." (PMID 26329009, 2015). "We used primers for the gene sequences of UBB, ESR1 (for luminal or ER/PR+ cancer cells), HER2 and GRB7 (for HER2+ cancer cells), EPCAM, KRT7, KRT8, KRT18, and KRT19, all of which have been commonly discussed for the purpose of breast cancer diagnosis." (PMID 28936247, 2015). "The positive detection rate of circulating cancer cells in breast cancer patients was only 43.9% when the single marker gene, cytokeratin 19, was employed." (PMID 24932314, 2014). "The three candidate markers, FAM83A, NPY1R and KRT19, were investigated further in a large cohort consisting of 142 breast cancer patients and 60 healthy controls, using the novel rapid nested PCR assay." (PMID 24932314, 2014). "Conversely, breast cancer patients with cytokeratin 19 mRNA copy number <2000 mostly presented a luminal subtype and a negative axillary lymph node dissection." (PMID 23533593, 2013). "Expression of keratin 8 and keratin 19 in the estrogen positive (ES+) breast cancer cell lines suggested that these cells had originated from luminal epithelial cells." (PMID 23599813, 2013). "Cytokeratin 19 (CK19) belongs to a family of keratins and is a type of cytoskeletal protein that is highly expressed in breast cancer cells." (PMID 24216695, 2012). "Our group has previously shown that the detection of CTCs in peripheral blood of early breast cancer patients before and after chemotherapy through the epithelial molecular marker Cytokeratin-19 (CK-19) is of prognostic significance." (PMID 21967632, 2011). "The detection of cytokeratin-19 (CK-19) mRNA-positive circulating tumor cells (CTC) before and/or after adjuvant chemotherapy in patients with operable breast cancer is associated with poor clinical outcome." (PMID 21663668, 2011). "The main objective of this study was the direct comparison of the detection rate of cytokeratin-19 (CK-19) mRNA-positive CTCs and DTCs in paired samples of the peripheral blood and bone marrow obtained from patients with early breast cancer." (PMID 19623181, 2009). "PCR methodology for detection of breast cancer has most frequently employed mammaglobin (mam) and cytokeratin 19 (CK19) genes." (PMID 18289390, 2008). "To investigate expression levels of EGFR, HER2, PI3K, and Akt in circulating tumor cells, we used peripheral blood mononuclear cells from 32 cytokeratin-19 mRNA-positive patients with early (n = 16) and metastatic (n = 16) breast cancer." (PMID 18822183, 2008).
breast carcinoma (continued). "The usefulness of serum CYFRA 21-1 (cytokeratin-19 fragments) in monitoring the recurrence of breast cancer and in evaluating therapeutic effects was studied retrospectively." (PMID 15280913, 2004). "It has been well demonstrated that breast cancer cells express fragments of cytokeratin-19, which is one of the various kinds of cytokeratins comprising the intermediate filaments of the cytoskeleton." (PMID 15280913, 2004). "We previously reported that the positive rates of serum CYFRA 21-1, which reacts specifically with cytokeratin-19 fragments, in patients with stage IV or recurrent breast cancer were as high as those for CA 15-3 and superior to those for CEA." (PMID 15280913, 2004). "We have used polymerase chain reaction (PCR) to measure keratin 19 mRNA in order to detect breast cancer cells invading axillary lymph nodes." (PMID 8932347, 1996). "In breast cancer, KRT19 could bind and stabilize human epidermal growth factor receptor 2 (HER2) via inhibition of ubiquitin-proteasome-mediated degradation of HER2." (PMID 41345704, 2025). "While CuNPs’ general cytotoxicity has been documented, their specific impact on KRT19 expression across breast cancer subtypes is unknown, representing a critical research gap." (PMID 40806403, 2025). "Each of these was supported by (i) the upregulation of KRT18, KRT19, E-cadherin, and downregulation of vimentin in breast carcinoma; (ii) increased levels of GFAP, MAP2, and PSD-95 in astrocytoma; and (iii) increased NeuN, GAP-43, and NF200 levels in neuroblastoma." (PMID 39859209, 2025). "It has been discovered that KRT19 is highly expressed in a number of cancers, including lung adenocarcinoma, ovarian cancer, and breast cancer; and it promotes the growth and metastasis of these cancers and is thought to have some bearing on the prognosis of these cancer." (PMID 39453570, 2025). "Notably, studies have reported a significant correlation between low expression of KRT19 and poor prognosis in breast cancer." (PMID 38831933, 2024). "KRT19 is a promising biomarker for diagnosis and prognosis in ovarian cancer and may contribute to the onset and progression of breast cancer." (PMID 39682235, 2024). "KRT19 is one of the most important cytokeratins expressed in epithelial and mesothelial tissues, and its overexpression has been reported in more than 30 malignant neoplasms, including lung and breast cancer." (PMID 36331721, 2023). "Cytokeratin-19 (CK19) is also a suitable marker for identifying breast cancer cells." (PMID 40226410, 2023). "In addition, we drew a sankey diagram to show the distribution trend of KRT19 expression in breast cancer patients with clinical characteristics." (PMID 36292723, 2022). "Thus, all detectable CXCL12 that was associated with cancer cells in six consecutive surgical samples of human PDA, CRC, and breast cancer, respectively, is covalently bound to KRT19." (PMID 35046049, 2022). "Therefore, the relationship between KRT19 expression and its phosphorylation in breast cancer patients was explored using the TCGA database." (PMID 36292723, 2022). "Here, we show that cancer cells of human pancreatic ductal adenocarcinoma (PDA), colorectal cancer, and breast cancer are coated with transglutaminase-2 (TGM2)–dependent covalent CXCL12–keratin-19 (KRT19) heterodimers that are organized as filamentous networks." (PMID 35046049, 2022). "We found that amplification was the main form of KRT19 alteration in breast cancer patients." (PMID 36292723, 2022). "Interestingly, KRT19 mRNA was previously used with great success for DTC detection in breast cancer, both in our research group and in other groups." (PMID 35659265, 2022). "Based on the results of this study, we suggest that the expression of KRT19 may influence breast cancer development by affecting the IL-17 signaling pathway." (PMID 36292723, 2022).
breast carcinoma (continued). "In breast cancer, positivity for KRT19 in the metastatic setting may range between 30 and 80%, whereas in patients with non-metastatic breast cancer, percentages are generally around 20%, although some studies reported higher values up to 60%." (PMID 36428760, 2022). "It is suggested that KRT19 methylation and phosphorylation may play an important role in the occurrence and development of breast cancer, which needs further experiment to test and verify." (PMID 36292723, 2022). "Moreover, KRT19 has been found to be highly upregulated in breast cancer with expression that significantly correlates with cell proliferation, migration, invasion, and prognosis." (PMID 34732768, 2021). "However, studies in breast cancer cells have shown that modulation of KRT19 expression led to contrasting effects on cell behaviors." (PMID 35096583, 2021). "KRT19 expression also correlates with poor prognosis in patients with breast cancer." (PMID 32519739, 2020). "Hence, the level of cytokeratin 19 in breast cancer cells can likely regulate ER stress induction to promote malignant cell dormancy." (PMID 31963677, 2020). "Cytokeratin19 (KRT19) can be used as a target in HER2-positive breast cancers." (PMID 33171868, 2020). "We found strong expression of KRT19 specifically in colon and breast cancer cells." (PMID 30650643, 2019). "Furthermore, BEP inhibited EMT of breast cancer cells, which was determined by an increased gene expression of the epithelial gene, keratin 19, and decreased gene expression of the mesenchymal gene, vimentin when compared to control." (PMID 30691094, 2019). "Then, we tried to silence KRT19 expression by transducing control shRNA (scramble) and KRT19 targeted shRNA (shKRT19) into both colon and breast cancer cell lines (i.e., HCT116, HT29, MDA-MB231, and MCF7 cells), and the knockdown effect was confirmed by RT-PCR and Western blot analyses." (PMID 30650643, 2019). "Recently, we showed that KRT19 has the ability to reprogram breast cancer." (PMID 30650643, 2019). "Mechanistically, in our previous study, we also found that KRT19 interacted with the β-catenin/RAC1 complex in breast cancer and was subsequently imported into the NUMB promoter in the nucleus, consequently regulating cancer properties through the Notch signaling pathway." (PMID 30650643, 2019). "Moreover, an altered role for KRT19 was observed in HER2+/HER2− breast cancer that relied on the level of KRT19 expression." (PMID 30650643, 2019). "The mRNA sequence of KRT19 shows one silent mutation, located in the coiled part of its protein structure, in breast cancer but not in colon cancer." (PMID 30650643, 2019). "Therefore, further studies are needed to elucidate the role of KRT19 regarding differences in Wnt/Notch signaling crosstalk in colon and breast cancers." (PMID 30650643, 2019). "We examined whether KRT19 in both colon and breast cancers had similar inhibitory effects on breast cancer progression or opposite effects." (PMID 30650643, 2019). "In early breast cancer, the molecular detection of cytokeratin 19 (CK-19) mRNA-positive cells in peripheral blood before, during, and after adjuvant therapy is associated with worse prognosis, while their elimination seems to be an efficacy indicator of treatment." (PMID 31261917, 2019). "Moreover, KRT19 expression downregulated in more aggressive breast cancer tissue than normal and less aggressive tissue." (PMID 29747452, 2018). "Moreover, KRT19 is reported to be a tumor suppressor gene in breast cancer, which regulates the nuclear translocation of EGR1 to the PTEN promoter." (PMID 29747452, 2018). "However, KRT19 shows discrepant relationships with both breast carcinoma and chemotherapy resistance." (PMID 29747452, 2018). "We found that expression of KRT19 was attenuated in several patients-derived breast cancer tissues and patients with a low expression of KRT19 were significantly correlated with poor prognosis in breast cancer patients." (PMID 29747452, 2018).
breast carcinoma (continued). "We then checked the KRT19 expression in breast cancer using Oncomine database." (PMID 29747452, 2018). "So far, the function of KRT19 in breast cancer still remains to be revealed." (PMID 29747452, 2018). "Our previous study demonstrated that KRT19 could attenuate ALDH1high/CXCR4high/CD133high breast cancer stem cell-like cells (CSLCs) properties by regulating NUMB-mediated wnt/notch signaling crosstalk." (PMID 29747452, 2018). "However, the roles that are involved in KRT19-driven breast cancer stem cell-like cell reprogramming and drug sensitivity are yet to be elucidated." (PMID 29747452, 2018). "The KRT19 was significantly downregulated in ductal breast cancer tissue as compared to the normal tissue, although KRT19 expression was upregulated in other breast cancer studies (Oncomine)." (PMID 29747452, 2018). "Studies in breast cancer indicated that KRT19, one of the main cytoskeleton proteins of epithelial cells, is released by viable tumor cells, which may constitute a biologically active subset of breast cancer cells with high metastatic properties." (PMID 27711225, 2016). "The objective of this study was to evaluate the significance of matrix metalloproteinase 9 expression by immunohistochemistry as supporting marker to cytokeratin 19 mRNA in sentinel lymph nodes in breast cancer patients and to relate this expression with clinicopathological data." (PMID 27110764, 2016). "In addition, the current study identified a novel panel of marker genes (FAM83A, NPY1R and KRT19) for the detection of cancer cells in the peripheral blood of breast cancer patients." (PMID 24932314, 2014). "Furthermore, the marker gene, KRT19, showed positive expression in 21 breast cancer patient samples, however, only one patient expressed the gene in the healthy control group." (PMID 24932314, 2014). "Other studies used sentinel lymph node analysis using one-step nucleic acid amplification (OSNA) has been proposed for intraoperative staging of breast cancer, and in these studies cytokeratin 19 (CK19) was considered as the most appropriate marker due to its broad expression in breast carcinomas." (PMID 23451192, 2013). "Furthermore, the detection of cytokeratin 19 (CK-19) and of mRNA-positive circulating tumor cells (CTCs) in the peripheral blood and the bone marrow of patients with breast cancer was correlated with increased incidence of relapse in several studies." (PMID 16846533, 2006). "Therefore, we further explored the genetic alterations in KRT19 in breast cancer." (PMID 36292723, 2022). "Additionally, we analyzed whether the overexpression of KRT19 (CK19) has a significant impact on breast cancer patients’ overall survival." (PMID 34884588, 2021). "Finally, novel metastatic biomarkers of KRT18 and KRT19 were detected in breast cancer CTCs." (PMID 34801010, 2021). "Thus, NUMB transcriptional activity might play a pivotal role in the contrasting effects of KRT19 knockdown in colon and breast cancers." (PMID 30650643, 2019). "In addition, four cytokeratin genes (KRT8, KRT16, KRT17, and KRT19) and eight tumor-associated genes (TERT, MUC16/M17S2/CA125, CD44, TWIST1, TACSTD1/EpCAM/CD326/ESA/HEA125/GA733, DPP4/CD26, ESR1, and PGR), were upregulated in CRC and breast cancer samples." (PMID 29882767, 2018). "Moreover, quantitative molecular diagnosis including carcinoembryonic antigen (CEA) and cytokeratin-19 (CK-19) assays targeting cancer cells in axillary WF revealed that CEA and CK-19 were predictor for locoregional recurrence in breast cancer patients with mastectomy." (PMID 26313265, 2015). "Likewise, the analysis of hMAM (human mammaglobin A), the most widely studied marker after CK19 (cytokeratin 19) in breast cancer patients, gene expression identifies patients with nearly 100% specificity at the same sensitivity as CK19 (1 tumor cell in 106 peripheral blood mononuclear cells)." (PMID 21129172, 2010).
breast carcinoma (continued). "So far no expression of HMGI-C in the peripheral blood of healthy controls could be found, which is of advantage, since the specificity of other RT–PCR assays in breast cancer, such as RT–PCR for cytokeratin 19, had to be questioned due to an expression in healthy controls." (PMID 12778070, 2003). "Synthesized via pulsed electrochemical dissolution, CuNPs exhibit cytotoxicity by impairing cellular structures, including intermediate filaments like Keratin 19 (KRT19), which is overexpressed in aggressive breast cancer subtypes." (PMID 40806403, 2025). "Cytokeratin 19 (CK19), found in epithelial cells, is a common immunohistochemical marker in breast cancer diagnosis." (PMID 38256428, 2024). "And TAGLN, ASPN, KRT19 and MGST1 have important roles in the prognosis, invasion, metastasis and drug resistance of breast cancer." (PMID 37470685, 2023). "This rapid molecular detection procedure analyses homogenized SLN by rapid real-time amplification and quantifies Cytokeratin 19 (CK19) mRNA copy numbers, which are expressed in most breast cancer cells." (PMID 35884447, 2022). "Frozen sections of surgically resected MSS PDA, MSS CRC, and breast cancer were stained with fluorochrome-conjugated antibodies to CXCL12 and keratin-19 KRT19." (PMID 35046049, 2022). "In breast cancer (GSE77308), KRT19 and SPANXB1 were shown to be correlated with several functional states." (PMID 35096583, 2021). "The plakoglobin (JUP), KRT8, KRT18, KRT19, CLDN4, and EPCAM, which their role in breast cancer metastasis was demonstrated in previous studies, are EMT markers." (PMID 34801010, 2021). "The KRT19-positive detections correlated with the diagnosis and high proliferation rate of breast cancer, and the combined positive detection of PTHRP-plus-KRT19 correlated with the presence of distant metastasis, especially with bone metastasis." (PMID 35096583, 2021). "In this current study, we conducted co-immunoprecipitation (Co-IP) and found that KRT19 interacts with β-catenin alone in colon cancer cells and with the β-catenin/RAC1 complex in breast cancer cells." (PMID 30650643, 2019). "In breast cancer cells, both nuclear RAC1 and β-catenin levels decreased upon KRT19 knockdown, which supports the evidence that RAC1 directly regulates β-catenin nuclear translocation." (PMID 30650643, 2019). "We found that the effect of KRT19 knockdown on Wnt/β-catenin signaling target genes was quite similar except for NUMB expression in both colon and breast cancer cells." (PMID 30650643, 2019). "Cytokeratin 19 fragments (CK19) are expressed in almost all epithelial malignancies, including breast cancer, lung cancer, colorectal carcinoma, cervical carcinoma, and papillary thyroid carcinoma." (PMID 29854023, 2018). "In our current study, we have reported a relationship between KRT19 (cytokeratin 19) expression with CSC reprogramming, and drug sensitivity in breast cancer and cancer stem cell-like cells." (PMID 29747452, 2018). "Thus, our data suggest that KRT19 might function as a promising tumor suppressor gene for targeting highly aggressive patient-derived ALDH1high, CXCR4high, and CD133high breast cancer stem cell-like cells, and could enable cancer cell reprogramming to less aggressive and more drug-sensitive cells." (PMID 29747452, 2018). "The EPCAM-positive breast-cancer cells and colon-cancer cells expressed EPCAM on all 96 h, whereas they only expressed KRT19 and CDH2 from 0 to 72 h." (PMID 28975085, 2017). "The positive detection rate of circulating cancer cells in breast cancer patients was 33.1 (47/142), 38.7 (55/142) and 43.7% (62/142) for the FAM83A, NPY1R and KRT19 genes, respectively." (PMID 24932314, 2014). "In conclusion, the current study developed a novel rapid nested PCR assay to detect circulating cancer cells in the blood of breast cancer patients using a novel panel of marker genes, FAM83A, NPY1R and KRT19." (PMID 24932314, 2014).